EZH2 (enhancer of zeste 2 polycomb repressive complex 2 subunit)
Diseases named in the same sentence as EZH2 in open-access papers (continued):
Sharing a sentence is not in itself a finding about the gene and the disease.
mesothelioma (continued). "In addition, we also determined whether existing a difference in the tumor immune microenvironment between mesothelioma patients with high or low EZH2 levels." (PMID 36195655, 2022). "Furthermore, we also sought to determine whether there lies a difference in the tumor immune microenvironment between mesothelioma patients with high or low EZH2 levels." (PMID 36195655, 2022). "Interestingly, inter- and intra-chromosomal rearrangements affected genes like CDKN2A, one of the most frequently mutated in mesothelioma and KDM6A, a gene that has been associated with sensitivity to enhancer of zeste homolog 2 (EZH2) inhibitors, like tazemetostat." (PMID 34249695, 2021). "To verify whether EZH2 inhibition could be therapeutically exploited in E-MpM, we treated SSL1 (the spontaneous stabilised cell line obtained from an epitheliod mesothelioma) with the EZH2 inhibitor GSK 126, which lead to a reduction in growth and a decrease in SLUG transcription." (PMID 27705913, 2016). "In this study, we employed a quantitative proteomic mass spectrometry approach to assess alterations in protein expression following EZH2 inhibition in BAP1- and CDKN2A-proficient mesothelioma cells cultured as spheroids." (PMID 41226368, 2025). "One study further showed that EZH2 inhibition resulted in reduced tumor size in mice with BAP1-inactivated mesotheliomas compared to wild-type mesotheliomas, providing evidence for the potential role of BAP1 in mediating tumor sensitivity to EZH2 inhibition." (PMID 38610930, 2024). "Here, we observe that EZH2 inhibitors dramatically enhance the efficacy of FGFR inhibition, sensitising BAP1-mutant mesothelioma and uveal melanoma cells." (PMID 38054839, 2024). "In line with this, we found enrichment for ERGs (P value = 3.4 × 10−3), including the mesothelioma drivers NCOR2 and EZH2, among the genes highly expressed in CIMP-high tumors, and more generally in the list of MPM drivers (q value = 2.1 × 10−5)." (PMID 36928603, 2023). "Specific EZH2 inhibitors (e.g., tazemetostat, EPZ-6438) decreased cell proliferation and reduced invasion and clonogenic capacity in mesothelioma cell lines and in in vivo experiments." (PMID 33802313, 2021). "To investigate whether a combined treatment of EZH2 and FGFR inhibition is effective, we made use of mouse mesothelioma cell lines derived from our genetically defined BNC (Bap1−/−, Nf2−/−, Cdkn2ab−/−) and NC (Nf2−/−, Cdkn2ab−/−) mice." (PMID 38054839, 2024). "In a non-mesothelioma setting, a patient with SMARCB1-deleted, metastatic, poorly differentiated chordoma was treated with Tazemetostat (EZH2 inhibitor), and had a significant increase in intratumoral and stromal infiltration by immune cells expressing checkpoint regulators PD-1 and LAG-3." (PMID 33952230, 2021). "The lack of BAP1 will induce mesothelioma cells sensitive to EZH2 drug inhibition." (PMID 36195655, 2022). "Interestingly, the frequency of EZH2, Survivin and BAP1 expression was similar in both low grade and high grade mesotheliomas, as well as in various growth patterns indicating that the combination of these markers is equally or similarly sensitive among all these morphological variants." (PMID 34257556, 2021). "However, the studies on the correlation of EZH2 with mesothelioma are still lacked, remaining the role in mesothelioma unknown." (PMID 36195655, 2022). "An enhanced sensitivity to EZH2 inhibition was reported in mesothelioma cells lacking BAP1, and related to enhanced expression of SETD8, a methyl transferase that decreased EZH2 expression and further restricted cell proliferation in these cells." (PMID 28122578, 2017).
colitis (28 papers, 2015 to 2025). Inflammation of the colon. "In line with the patients' lower levels of EZH2 expression, the inactivation of EZH2 in IECs sensitizes mice to experimental colitis caused by DSS and TNBS." (PMID 39118979, 2024). "Previous studies have demonstrated that suppressing EZH2 activity ameliorated experimental intestinal inflammation and delayed colitis-associated cancer progression." (PMID 35432300, 2022). "In this case, while global inhibition of EZH2 activity or myeloid-specific Ezh2 deletion ameliorates experimental intestinal inflammation the loss of Ezh2 in either the intestinal epithelium or regulatory T cells results in a spontaneous colitis phenotype." (PMID 34088983, 2021). "It was recently reported that suppressing EZH2 activity ameliorates experimental intestinal inflammation and delays the onset of colitis-associated cancer." (PMID 33724181, 2021). "Here we report that suppressing EZH2 activity ameliorates experimental intestinal inflammation and delayed the onset of colitis-associated cancer." (PMID 31160593, 2019). "A recent study reported that systemic inhibition of EZH2 protein expression by DZNep results in heightened susceptibility to DSS-induced colitis, which is associated with an activated, effector phenotype of Treg cells." (PMID 31160593, 2019). "In keeping with these data we returned to our transfer colitis model and compared the ability of control and Ezh2-deficient naïve T cells to induce transfer colitis." (PMID 26090605, 2015). "By contrast, mice that received WT naïve CD4+ T cells together with Ezh2-deficient Treg cells developed colitis and lost weight, suggesting that Ezh2-deficient Tregs were functionally defective." (PMID 26090605, 2015). "In addition, it was shown that EZH2 suppression ameliorate intestinal inflammation and delay the onset of colitis associated cancer, suggesting the feasibility of EZH2 inhibitor for the control of IBD." (PMID 38510241, 2024). "It was demonstrated that decreased EZH2 levels sensitize mice to experimental colitis, whereas overproduction of EZH2 in the intestinal epithelial cells reinforces their resistance to inflammatory conditions." (PMID 40723311, 2025). "The FBXW7/EZH2/CCL2/CCL7 pathway has been shown to exacerbate colitis severity by recruiting CX3CR1 proinflammatory MPhs." (PMID 39568749, 2024). "Mechanistically, our results highlight an epigenetic mechanism by which YAP inhibits the inflammatory response in colitis through epigenetic silencing of JMJD3 by binding to EZH2." (PMID 38245781, 2024). "Our findings elucidate an epigenetic mechanism by which YAP inhibits the inflammatory response in colitis through epigenetic silencing of JMJD3 by recruiting EZH2." (PMID 38245781, 2024). "SCFFBW7 mediates the degradation of EZH2 and promotes the CX3CR1int mononuclear phagocyte recruitment into colitis-affected colon tissues." (PMID 37006236, 2023). "Specifically, therapeutically targeting EZH2 activity not only reduces colitis-related symptoms and extends the survival of colitic mice, but, even more remarkably, this therapeutic approach also delays CAC and reduces tumor burden." (PMID 31160593, 2019). "Here we report that interference with EZH2 activity using pharmacological inhibitors attenuates dextran sodium sulfate (DSS)-induced colitis and delays the onset of CAC." (PMID 31160593, 2019). "Here we demonstrated, for the first time, that interfering with EZH2 activity using low doses of pharmacological inhibitors ameliorates DSS-induced colitis." (PMID 31160593, 2019). "Here, the authors show that EZH2 inhibitors attenuate experimental colitis in mice by promoting the development of myeloid-derived suppressor cells, and delay the onset of colitis-associated cancer." (PMID 31160593, 2019). "Having identified an essential role for EZH2 in DSS-induced colitis, we employed a second intestinal inflammation model, indomethacin-induced enteropathy, to substantiate and expand on this idea." (PMID 31160593, 2019).
colitis (continued). "Besides, EZH2 is considered critical for the recruitment and immunosuppression function of activated regulatory T cells (Tregs) at the sites of inflammation, and EZH2-deficient Tregs fail to protect mice from the development of autoimmunity in a model of naïve T cell-mediated colitis." (PMID 29556394, 2018). "EZH2 overexpression in the intestinal epithelium provides more resistance to colitis in mice." (PMID 39865190, 2025). "However, suppressed EZH2 by Fbxw7 in macrophages promoted intestinal inflammation, and inactivation of EZH2 in epithelial cells sensitizes mice to experimental colitis, indicating an anti-inflammatory effect of EZH2." (PMID 38243324, 2024). "Furthermore, rectal Insulin instillation promotes EZH2 expression and the EZH2 inhibitor GSK126 alleviates colitis." (PMID 38243324, 2024). "Notably, SCFFBW7 promotes the progression of colitis through mediating the ubiquitination and degradation of the histone-lysine-N-methyltransferase enhancer of zeste homolog 2 (EZH2)." (PMID 37006236, 2023). "Indeed, the enhanced pro-inflammatory effect of Ezh2 blockage is mentioned via (i) increased tumoricidal impact of tazemetostat (an Ezh2 inhibitor) and (ii) worsened colitis after Ezh2 downregulation." (PMID 37239864, 2023). "Recently, a report displayed that inhibition of EZH2 activity could improve the symptoms of experimental enteritis and delay the development of colitis-related cancers." (PMID 36569895, 2022). "Additionally, Ezh2 deficiency improved the outcome on EAE and colitis, two inflammatory mouse models." (PMID 33574814, 2020). "Interestingly, our data demonstrate that systemic inhibition of EZH2 histone methyltransferase activity by GSK343 ameliorates DSS colitis." (PMID 31160593, 2019). "To further address whether inhibition of EZH2 can ameliorate ongoing DSS-induced colitis, we therapeutically treated DSS-induced mice with GSK343." (PMID 31160593, 2019). "have documented that EZH2 deficiency suppressed M1 polarization and attenuated the inflammatory responses through the SOCS3/STAT1 pathway, leading to the suppression of autoimmune inflammation diseases including DSS-induced colitis in an experimental autoimmune encephalomyelitis (EAE) model." (PMID 35432300, 2022). "Moreover, EZH2-deficient Tregs failed to protect mice from developing autoimmunity in a model of naïve T cell-mediated colitis." (PMID 33180829, 2020). "Therefore, inhibition of EZH2 activity during colitis delays the onset of CAC." (PMID 31160593, 2019). "Therefore, we reasoned that inhibition of EZH2 activity during colitis development may affect the development of CAC." (PMID 31160593, 2019). "Thus, H3K27Me3-independent EZH2 activity may also contribute to DZNep-mediated exacerbation of DSS-induced colitis." (PMID 31160593, 2019). "To test if deficiency of EZH2 in Treg cells could alter the expansion of Treg and T effector cells in vivo, we also measured the percentages of Treg and T effector cells in the CD4 compartment at the end of colitis induction." (PMID 26090605, 2015). "We identified that YAP inhibits the colitis inflammatory response and promotes intestinal epithelial barrier repair through epigenetic silencing of JMJD3 by binding to EZH2." (PMID 38245781, 2024). "EZH2 reduction directly stimulates TRAF2/5 expression to enhance TNFα-induced NF-κB signaling, and promote inflammation and apoptosis in colitis." (PMID 39588368, 2024). "For example, histone 3 lys27 tri-methyltransferase Ezh2 epigenetically inhibited antiinflammatory mediator Socs3 in macrophages by mediating H3K27me3, which promoted autoimmune inflammation in DSS-induced colitis and experimental autoimmune encephalomyelitis." (PMID 37733446, 2023). "Our study found that rectal insulin instillation exacerbated colitis through the regulatory effect of EZH2 on TRM, suggesting that both insulin inhibitor and EZH2 inhibitor could be potential drugs for IBD treatment." (PMID 38243324, 2024).
colitis (continued). "It was shown that the inhibition of enhancer of zest homolog 2 (Ezh2), a major histone methyltransferase, promoted the differentiation of hematopoietic progenitor cells (HPCs) into MDSCs by activating the Janus kinase (JAK)-STAT and TNF signaling pathways in DSS-induced colitis." (PMID 40244120, 2025). "In conclusion, activation of the insulin pathway upregulates EZH2 expression in intestinal mucosal T cells during inflammation, which in turn promoted TRM differentiation and disrupted subgroups of IELs and inflammatory cytokines, ultimately exacerbated colitis." (PMID 38243324, 2024). "The degradation of EZH2 results in the inhibition of H3K27me3 modification and increases the expression of CCL2 and CCL7 in CXCR1hi macrophages, subsequently promoting the recruitment of CX3CR1int pro-inflammatory mononuclear phagocytes (MPhs) into colitis-affected colon tissues." (PMID 37006236, 2023). "However, in experimental model of autoimmune diseases including dextran sulfate sodium (DSS)-induced colitis and experimental autoimmune encephalomyelitis (EAE), EZH2 in the macrophage induced autoimmune disease progression, and inhibition of EZH2 reduced pro-inflammatory responses." (PMID 35432300, 2022). "In addition, inhibition of EZH2 activity with GSK126, a selective EZH2 inhibitor, contributed to the differentiation of hematopoietic progenitor cells into MDSCs in vitro, thereby ameliorating colitis symptoms, whereas depletion of MDSCs exacerbated disease progression." (PMID 36569895, 2022). "Consequently, mice lacking Ezh2 in their macrophages showed improved outcome in models for autoimmune inflammation, experimental autoimmune encephalomyelitis (EAE) and colitis." (PMID 33574814, 2020).
prostate tumor (28 papers, 2010 to 2026). "UHRF1 and EZH2 were previously linked for their paralleled functions in keratinocyte self-renewal and for their positive correlation in human prostate tumor samples." (PMID 35169042, 2022). "Moreover, EZH2 plays a direct causal role in driving prostate tumor progression and metastasis in animal models." (PMID 37104245, 2023). "Contrary to PTEN, there was a positive correlation between INPP4B and EZH2 expression in normal human prostates and early-stage prostate tumors." (PMID 38001678, 2023). "In support of their relevance to progression, we found that ERG/EZH2 coregulated targets were significantly deregulated in CRPC compared to primary prostate tumors." (PMID 34230470, 2021). "Another recent study found that USP44 deubiquitinates and stabilizes the expression an activity of the histone methyltransferase EZH2 in prostate tumor cells as well as oncogenic mutants of this epigenetic factor with pro‐tumor results." (PMID 32644293, 2020). "Here, knockdown of EZH2 in the PC3 prostate tumor model enhanced polymerization of F-actin and formation of actin-rich filaments." (PMID 33327550, 2020). "To obtain further insight into the expression of EZH2 in cancer, we analyzed transcriptome data from a publicly available study on 131 primary prostate tumors and 19 metastases." (PMID 26637281, 2015). "MSMB codes for a secreted seminoprotein, which has tumour suppressor properties and is thought to be silenced in prostate tumour tissues by the enhancer of zeste homolog 2 (EZH2) protein." (PMID 20569440, 2010). "We show that Nkx3.1 is directly controlled by ERG and ESE3 in prostate tumors and EZH2 contributes to its silencing." (PMID 20479932, 2010). "Consistent with a hypothesis of compensatory downregulation of EZH2 in early prostate tumorigenesis, the positive correlation between INPP4B and EZH2 is only evident in the primary prostate tumors." (PMID 38001678, 2023). "Furthermore, synergistic decreases in prostate tumor growth were noted following in vivo exposure to metformin and EZH2 inhibitors." (PMID 36175875, 2022). "Although significant progress has been made toward understanding the function and deregulation of EZH2 in PCa cells in vitro and prostate tumors in vivo, it remains largely unclear regarding how the novel regulatory mechanisms of EZH2 can be translated to effectively kill CRPC cells." (PMID 26657505, 2016). "Indeed, although studies have demonstrated that EZH2 is frequently overexpressed in a wide variety of cancers including tumors of the prostate and breast, mechanistic links of EZH2 to cancer progression remain areas of intense investigation." (PMID 22563434, 2012). "Further, the results implicate EZH2-driven mechanisms by which Myc may stimulate prostate tumor initiation and disease progression." (PMID 21941025, 2011). "We observed that there was an inverse relation between ESE3 and EZH2 expression in prostate tumors." (PMID 20479932, 2010). "By disrupting both the expression and interaction of key m6A MTC subunits, combinational treatment of EZH2 degrader MS8815 and m6A inhibitor STM2457 mitigates prostate tumor growth synergistically." (PMID 41252201, 2026). "These included EZH2 in DNA hypermethylated regions of prostate tumors in AA and EA men and CTCF in hypomethylated regions of only prostate tumors in AA men." (PMID 38566104, 2024). "Data from TCGA databases suggested that SNHG4 expression was significantly correlated with the expression of RRM2, EZH2, AURKA and TK1 in prostate tumor samples (p < 0.01)." (PMID 37596700, 2023). "In contrast, both benign prostates and prostate tumors in the PtenLoxP/LoxP, PB4-Cre males expressed significantly higher levels of Ezh2 than the prostates of the WT males (GSE76822, GSE56469, and GSE98493)." (PMID 38001678, 2023). "S5E), these data demonstrate that HIF1A promotes the expression of EZH2 and SOX2 under both hypoxic and normoxic conditions and enhances the progression of prostatic tumors." (PMID 35867798, 2022).
prostate tumor (continued). "Consistently, similar clusterization was observed for the mERG/EZH2 targets with both significantly enhanced (50%) and attenuated (50%) genes in CRPC versus primary prostate tumors." (PMID 34230470, 2021). "In summary, the present study demonstrates that miR-141, devoid in PCSCs, suppresses prostate tumour growth and metastasis by targeting a cohort of prometastasis genes including CD44, EZH2 and Rho GTPases." (PMID 28112170, 2017). "5-AZA-CdR in combination with the EZH2 inhibitor, GSK-126, inhibited the in vivo growth of a prostate tumor xenograft more effectively than treatment with 5-AZA-CdR alone." (PMID 28261562, 2017). "However, few factors have been identified that might increase EZH2 expression in prostate tumors." (PMID 20479932, 2010). "Importantly, co-IP with the anti-EZH2 antibody and immunoblotting, showed that ERG and EZH2 interacted and was methylated in ERG fusion positive human primary prostate tumors." (PMID 34230470, 2021). "For example, EZH2-S21phospho may reduce EZH2 binding to histone H3 and enhance its interactions to non-PRC2 partners, such as androgen receptor (AR) in advanced prostate tumor and STAT3 in GBM." (PMID 33327550, 2020). "Collectively, numerous complimentary and cross-validating approaches we took in our studies deliver a clear message that miR-141 possesses prostate tumour and metastasis suppressive functions via targeting critical molecules including CD44, Rho GTPases and EZH2." (PMID 28112170, 2017). "In the context of prostate tumor development and progression, we speculate that the epigenetic suppression of ATF3 by EZH2 by might be an important protective mechanism that promotes survival as tumors develop/progress and are subject to increasing cellular and environmental insults." (PMID 37104245, 2023). "However, we provide additional insights showing that the non-canonical function of EZH2 in ERG-positive prostate tumors involves the direct interaction, methylation, and functional cooperation with ERG resulting in enhanced trans-activation of selected co-regulated target genes." (PMID 34230470, 2021). "The enhancer of zeste homolog 2 (Drosophila) (EZH2), a histone methyltransferase, was upregulated in fusion negative prostate tumor and controlled by miR-26a." (PMID 24739220, 2014).